DAB2IP (DAB2 interacting protein)
Diseases named in the same sentence as DAB2IP in open-access papers (continued):
Sharing a sentence is not in itself a finding about the gene and the disease.
cancer (continued). "Next, we checked whether the mutation frequencies of PRRT2 and DAB2IP observed in the cancer cell line panels could be confirmed in primary cancer samples." (PMID 27907910, 2017). "Several reports indicate the genetic variation of DAB2IP is associated with the risk of cancer." (PMID 26658103, 2016). "Decreased expression of tumor suppressor DAB2IP is linked to aggressive cancer and radiation resistance in several malignancies, but clinical survival data is largely unknown." (PMID 26471467, 2015). "Consistent with its role as an inhibitor of cell survival and growth, DAB2IP expression is often down-regulated in several human cancers, which is frequently associated with the promoter hypermethylation or enhancer of zeste homolog 2 (EZH2)-mediated transcriptional silencing." (PMID 26336990, 2015). "In general, loss of DAB2IP in cancer cells is due to its epigenetic silencing." (PMID 25115390, 2014). "Furthermore, we demonstrated that DAB2IP-low Luminal A tumors exhibited more shallow genomic deletions compared with the DAB2IP-high group, also indicating that loss of DAB2IP expression was associated with more aggressive cancer phenotypes." (PMID 39418101, 2024). "We focused on thiostrepton, finding evidence that DAB2IP upregulation can contribute to its ability to counteract the aggressiveness of cancer cells." (PMID 40867592, 2025). "Based on this assumption, we performed a drug-repurposing screen to search for molecules capable of increasing the levels of DAB2IP in cancer cells." (PMID 40867592, 2025). "Using this approach, we uncovered candidate molecules able to modulate DAB2IP levels in cancer cells." (PMID 40867592, 2025). "Based on this evidence, DAB2IP can be considered a strong candidate for the development of therapeutics aimed at increasing its protein levels in cancer cells, thus restoring its onco-suppressive role." (PMID 40867592, 2025). "Taken together, these results indicate that upregulation of DAB2IP can contribute to the cancer-inhibitory action of thiostrepton, with potential implications for the clinical repurposing of this drug." (PMID 40867592, 2025). "Solid experimental evidence shows that DAB2IP reactivation reduces cancer aggressiveness in tumors driven by multiple different oncogenic mutations, making this protein an interesting target for cancer therapy." (PMID 40867592, 2025). "We identified individual genes upregulated in DAB2IP-low Luminal A tumors that are known to play important roles in cancer progression and therapy resistance." (PMID 39418101, 2024). "The loss of expression or activity of tumor suppressor proteins, including DAB2IP is a common theme across cancers." (PMID 39418101, 2024). "DAB2IP is inactivated in cancers through promoter methylation involving the EZH2-PRC2 complex, phosphorylation by AKT1, posttranscriptional silencing by microRNAs, and degradation by E3-ubiquitin ligases." (PMID 39418101, 2024). "For instance, BIRC5 was upregulated in DAB2IP-low Luminal A tumors, and its expression has been proposed to drive the progression of breast and other cancers." (PMID 39418101, 2024). "As we have summarized here, several independent studies confirmed that ectopic overexpression of DAB2IP is sufficient to counteract oncogenic phenotypes in different cancer models." (PMID 38902547, 2024). "Although the molecular mechanism was not explored, the data suggest that a soft extracellular environment induces DAB2IP downregulation and this facilitates acquisition of a cancer stem cell-like phenotype." (PMID 38902547, 2024). "Despite DAB2IP being a rather stable protein, various ubiquitin-ligases have been reported to influence its turnover in cancer cells." (PMID 38902547, 2024). "In fact, a recent study showed that xenografted tumors developed from DAB2IP-knockdown cancer cells have higher micro-vascular density and increased radioresistance." (PMID 38902547, 2024).
cancer (continued). "In particular, we explore potential approaches aimed at reactivating DAB2IP, or augmenting its expression levels, as a novel strategy in cancer treatment." (PMID 38902547, 2024). "DAB2IP plays a critical role in suppressing stemness through various mechanisms in other cancer types." (PMID 37443071, 2023). "Despite substantial knowledge about its pathological downregulation in cancer, very little is currently known about the regulation of DAB2IP in physiological conditions." (PMID 37444489, 2023). "DAB2IP suppresses the development of CSCs by introducing different regulatory mechanisms in various types of cancer." (PMID 37443071, 2023). "Inhibition of DAB2IP expression conferred cancer stem cell capacity and chemoresistance in TNBC cell lines." (PMID 36536485, 2022). "DAB2IP has Ras-GTPase activity and has been shown in various cancers to inhibit the cancer stem cell phenotype." (PMID 36359771, 2022). "DAB2IP prohibits cancer cell proliferation, survival and migration via regulating various oncogenic signalling (including the PI3K‐AKT, RAS‐MAPK, JAK‐STAT pathways)." (PMID 36536485, 2022). "Studies have shown that DAB2IP inhibits cancer progression, while HSP90AA1 promotes cancer progression." (PMID 35590292, 2022). "Previous studies indicated that DAB2IP is involved in the control of Wnt/β‐catenin pathway in human cancers." (PMID 36536485, 2022). "PCa cells with DOC-2/DAB2 interactive protein (DAB2IP) knockdown were chosen to imitate the cancer stem cells (CSC) with radioresistant phenotype." (PMID 33557143, 2021). "DAB2IP contains two potential phospho-degron sequences, with homology to consensus Fbw7 substrates, and degradation of DAB2IP by Fbw7/SCF in cancer cell lines possibly requires CKδ-mediated phosphorylation." (PMID 33096593, 2020). "Various additional miRNAs have been described to target DAB2IP in different cancers, and it is reasonable to predict that more will be discover in the future." (PMID 33096593, 2020). "In various cancer types, DAB2IP has been shown to control cell proliferation, apoptosis, and cell survival by inhibiting the Ras/MAPK pathway, activating the Ask1/JNK pathway, and inhibiting the PI3K/Akt pathway, respectively." (PMID 32943609, 2020). "Clinical data indicated that DAB2IP was down-regulated in different human cancers, including prostate, lung, liver, and bladder." (PMID 30459405, 2018). "Upregulation of miR-889, an oncogenic miRNA, increases cancer cell proliferation, radiation resistance, metastasis, and decreases apoptosis by inhibiting DAB2IP expression." (PMID 30546829, 2018). "Among identified candidate genes, DAB2IP is a Ras GTPase-activating protein and plays a cancer suppressor role in tumorigenesis." (PMID 27768594, 2016). "Down-regulation of DAB2IP in several cancers is mainly due to altered epigenetic regulation of its promoter." (PMID 26336990, 2015). "Further analysis showed that the samples of low DAB2IP expression, on the average, had more than a 7% increase in the percentage of CD133+ cancer cells than those of high DAB2IP expression." (PMID 26564738, 2015). "Evidences show that down-regulation of DAB2IP in cancer is mediated by polycomb EZH2 and histone deacetylase." (PMID 26336990, 2015). "Our recent data demonstrated that loss of DAB2IP in PCa cells elicited epithelial-to-mesenchymal transition (EMT), leading to cancer metastases and radio-resistance." (PMID 25015118, 2014). "Considering the biological safety and low CDT concentration administered in cancer therapy, our study supports the utilization of CDT in therapy for radio-resistant PCa, particularly in cases with loss of DAB2IP expression." (PMID 25015118, 2014). "We have previously shown that loss of DAB2IP can increase EMT in PCa, leading to cancer metastases and radio-resistance." (PMID 25015118, 2014).
cancer (continued). "In fact, even a moderate increase in DAB2IP levels may be able to limit cancer aggressiveness, as we previously demonstrated by targeting some known mechanisms of DAB2IP inactivation." (PMID 40867592, 2025). "Interestingly, it appears that DAB2IP inactivation generates a pro-tumoral inflammatory microenvironment that affects both cancer progression and response to therapy." (PMID 38902547, 2024). "However, there are a few studies in which authors have been able to restore physiological levels, or functions, of DAB2IP in cancer cells by interfering with known mechanisms of its inactivation." (PMID 38902547, 2024). "Despite these potential pitfalls, pharmacological reactivation or upregulation of a single protein such as DAB2IP that negatively modulates multiple oncogenic pathways, could significantly improve treatment of many cancers with minimal side effects." (PMID 38902547, 2024). "This last evidence suggests that targeting the ubiquitin-ligases responsible of DAB2IP ubiquitination may be a therapeutic strategy to reduce cancer aggressiveness by increasing DAB2IP levels." (PMID 38902547, 2024). "Furthermore, knockdown of DAB2IP in T47D cells resulted in an increased expression of BUB1, which has been associated with the maintenance of cancer cell stemness." (PMID 39418101, 2024). "DAB2IP suppression promotes a cancer stem-like cell phenotype in ER+ luminal cell lines." (PMID 39418101, 2024). "In glioblastoma, overexpression of DAB2IP could lower the intrinsic resistance of these cancer cells to temozolomide." (PMID 38902547, 2024). "Together, these data support the hypothesis that cancer cells can induce a pro-metastatic TME by paracrine downregulation of DAB2IP in stromal cells." (PMID 38902547, 2024). "Finally, DAB2IP has been reported to inhibit the stem cell properties of cancer cells, with implications for progression and chemoresistance." (PMID 38902547, 2024). "Despite several unanswered questions regarding the mechanism, our experiments reveal two previously unreported features of DAB2IP biology that may have important implications for cancer." (PMID 37444489, 2023). "DAB2IP expression is frequently reduced in tumors by promoter methylation; in addition, post-transcriptional mechanisms of inactivation in cancer and stromal cells have been reported: these include repression by microRNAs, formation of aberrant protein complexes, and possibly increased degradation." (PMID 37444489, 2023). "DAB2IP can also suppress the stemness of cancer cells by impairing CD117 transcription." (PMID 34775484, 2022). "A recent study indicated that DAB2IP inhibited BC distant metastasis by inhibiting cancer EMT indicating that DAB2IP might also involve in the modulation of Wnt/β‐catenin pathway in BC." (PMID 36536485, 2022). "Among its effects, DAB2IP inhibits oncogenic processes and facilitates cancer cell apoptosis." (PMID 34140969, 2021). "DAB2IP negatively regulates various signaling pathway involved in cancer progression." (PMID 33710763, 2021). "Intriguingly, miR-889 is upregulated upon arsenite exposure via repression of its competitive circRNA-008913: the consequent DAB2IP downregulation and acquisition of cancer stem cell properties could partially explain the carcinogenic effect of arsenite." (PMID 33096593, 2020). "Besides the previously reported involvement in human cancer cells, DAB2IP shows a potentially imperative role in trophoblasts and pathologic pregnancy." (PMID 29163762, 2017). "Also here we identified CNOT1, DAB2IP and PRRT2 as novel MSI target genes, in the MMR-deficient cancer cell lines, although with varying frequency." (PMID 27907910, 2017).
cancer (continued). "Recently, DAB2IP has been found significantly down regulated in multiple types of cancer." (PMID 26658103, 2016). "Given that DAB2IP appears to have a significantly important role in tumorigenesis and metastasis, we review the current advances about the role of DAB2IP on cancer development, the molecular mechanisms leading to aberrant expression of DAB2IP, and its potential as a therapeutic target." (PMID 26658103, 2016). "Clinically, DAB2IP gene hypermethylation is correlated with the development of many cancer types." (PMID 27129174, 2016). "DAB2IP has been implicated in the regulation of a diverse array of biological processes including proliferation, apoptosis, epithelial-to-mesenchymal transition (EMT), cancer stem cell (CSC), autophagy and so on, and will be illustrated as follows." (PMID 26658103, 2016). "Altered DAB2IP gene expression often detected in cancers is due to epigenetic silencing." (PMID 26658103, 2016). "Most of these genes have not been previously reported in HCC, and BTBD17, MIR6089, ZNF205-AS1 and ZP1 have not previously been linked to cancer; only two genes (DAB2IP and ZNF185) have been reported in HCC." (PMID 27768594, 2016). "Recently, DAB2IP has been regarded as a critical suppressor in cancer progression." (PMID 26336990, 2015). "Together, these results demonstrate E2 may promote cancer progression through the ERs/EZH2/DAB2IP pathway." (PMID 26587829, 2015). "Using constitutively active Skp2, reduced DAB2IP protein was detected in 293 wild-type (wt) cells, Taken together, Skp2-mediated UPS plays an important role in regulating DAB2IP protein expression post-translationally in both immortalized normal prostate epithelial and cancer cells." (PMID 25115390, 2014). "This reciprocal regulation between DAB2IP and Skp2 protein represents a unique homeostatic balance between tumor suppressor and oncoprotein in normal prostate epithelia, which is apparently altered in cancer cells." (PMID 25115390, 2014). "Moreover, study also revealed a function of DAB2IP in modulating epithelial-to-mesenchymal transition and cancer metastasis." (PMID 22046421, 2011). "Interestingly, some of these evidences suggest that DAB2IP may be an important player in the cancer-stroma crosstalk." (PMID 38902547, 2024). "Clearly it is a difficult challenge, but an in-depth understanding of the molecular mechanisms involved in DAB2IP inactivation may enable the development of ad hoc strategies to manipulate its expression and function, that could have a relevant impact for cancer therapy." (PMID 38902547, 2024). "Notably, in vivo, DAB2IP-mediated inhibition of cancer growth and metastasis can be uncoupled." (PMID 38902547, 2024). "Moreover, miR-149-3p could promote cancer cell growth, invasiveness and dissemination by inhibiting DAB2IP expression in both cancer and stromal cells." (PMID 32624692, 2020). "Moreover, DAB2IP suppresses cancer stem cell properties via CD117-meidiated ZEB1 signaling pathway." (PMID 26336990, 2015). "It would be worth investigating if the anti-cancer effects of AKT inhibition in certain tumors are mediated, at least in part, by restoration of DAB2IP functions." (PMID 38902547, 2024). "DAB2IP, known for its Ras-GTPase activity, suppresses cancer stem cell phenotype in several cancers, and its repression by EZH2 promotes cancer cell stemness." (PMID 39620228, 2024). "In cancer, epigenetic modifications affect the expression of Enhancer of Zester Homolog 2 (EZH2), and silenced disabled homolog 2 interacting protein gene (DAB2IP) (onco-suppressor gene) by Histone H3 tri-methylation in lysine 27 (H3K27me3)." (PMID 31666665, 2019). "Since then, the functions of DAB2IP have extended to regulating cell proliferation, metastasis, EMT, cancer stem cell phenotype, radiation, and chemotherapy resistance." (PMID 29743885, 2018).
cancer (continued). "Reduced expression of DAB2IP in PCa cells also induces epithelial-mesenchymal transition (EMT), leading to cancer metastasis, and these cells acquire radio-resistance to ionizing radiation (IR)-induced apoptosis." (PMID 25015118, 2014). "Functional experiments revealed that the cancer-inhibitory effect of thiostrepton is reduced in the absence of DAB2IP, suggesting that upregulation of this protein contributes to its action." (PMID 40867592, 2025). "Additionally, terms related to signaling axes that are commonly hijacked by cancer cells, such as terms related to ALK, TROP2, and TOB1, which is a growth-suppressive factor, and EGFR and ERBB (leading genes DAB2IP and PTPRJ) were enriched in both analyses." (PMID 40564222, 2025). "We found that miR-149-3p is secreted by cancer cells and contributes to DAB2IP downregulation in non-transformed cells." (PMID 38902547, 2024). "This indicates that the clinical significance of low DAB2IP is not just limited to Luminal B cancer but also to the more common Luminal A subtype." (PMID 39418101, 2024). "Not surprisingly, the reconstitution of DAB2IP can increase the sensitivity of cancer cells to chemotherapy." (PMID 38902547, 2024). "In addition, we also observed that genes contributing to cancer cell stemness, such as CDKN3, BRIX1, TBCA, TMX2, and others, were highly expressed in the Luminal A DAB2IP-low tumors compared with the DAB2IP-high Luminal A tumors." (PMID 39418101, 2024). "We found that C4-2 cells expressing the DAB2IP 2A mutant, but not wild-type DAB2IP, exhibited increased aneuploidy, which is highly correlated with carcinogenesis and aggressive cancer cells." (PMID 34775484, 2022). "Previously, DAB2IP had been investigated in CRC and other cancers." (PMID 30770783, 2019). "In addition, downregulation of DAB2IP increased the EMT and enriched the cancer stem cell population of the PCa cells." (PMID 28081154, 2017). "Our group discovered the Skp-2 mediated UPS played an important role in regulating DAB2IP protein expression post-translation in both immortalized normal prostate epithelial and cancer cells." (PMID 26658103, 2016). "However, the transcriptional regulation of DAB2IP in cancer has not been illustrated." (PMID 26336990, 2015).
adenocarcinoma (1 paper, 2019). A common cancer characterized by the presence of malignant glandular cells. "The analysis of transcription showed lower levels of DAB2IP mRNA expression in A549 cell line (adenocarcinoma phenotype) than epithelial cell line16HBE." (PMID 31666665, 2019).
cardiovascular diseases (1 paper, 2014). "In addition, genome-wide association studies also indicate that single nucleotide polymorphism of DAB2IP gene is associated with not only the risk of aggressive PCa and other non-malignant diseases such as abdominal aortal aneurysm and cardiovascular diseases." (PMID 25115390, 2014).
DAB2IP also shares sentences with these, for which no sentence is quoted: gastrointestinal tumors (3 papers); medulloblastoma (2); pancreatic cancer (2); acute myeloid leukemia (1); amyotrophic lateral sclerosis (1); arteriosclerosis (1); autism (1); bladder tumors (1); endothelial dysfunction (1); gastric tumor (1); hyperlipidemia (1); hypertension (1); liver cancer (1); Luminal A (1); Mcc (1); metastatic cancers (1); neurodevelopmental disorder (1); papillary thyroid carcinoma (1); Parkinson disease (1); peripheral vascular disease (1); primitive neuroectodermal tumor (1); schizophrenia (1); Stillbirth (1).